MRPL22 (mitochondrial ribosomal protein L22)
Synonyms: L22mt; MRP-L22; MRP-L25; RPML25; HSPC158; uL22m
Tractability: Small molecule: a structure with a bound ligand is known. PROTAC: ubiquitination databases record sites on it; its protein half-life has been measured.
Gene: Protein-coding gene on chromosome 5 (154,941,073 to 154,969,411, forward strand). Ensembl gene ENSG00000082515.
Subcellular location: Mitochondrion
Subcellular location (Human Protein Atlas): Mitochondria
Pathways (Reactome):
Metabolism of proteins: Mitochondrial ribosome-associated quality control; Mitochondrial translation elongation; Mitochondrial translation initiation; Mitochondrial translation termination
Gene Ontology:
Molecular function: protein binding; RNA binding; structural constituent of ribosome
Biological process: mitochondrial translation; translation
Cellular component: mitochondrial large ribosomal subunit; mitochondrion; mitochondrial inner membrane; large ribosomal subunit; ribosome
Genetic constraint (gnomAD): Loss-of-function variants: 13 observed, 18.37 expected, observed/expected ratio (o/e) 0.71, 90% interval 0.46 to 1.12. The upper end of that interval is the gene's LOEUF score, 1.12, which puts it in group 4 of 6, group 1 being the genes least tolerant of losing a copy. Missense variants: 182 observed, 207.35 expected, observed/expected ratio (o/e) 0.88, 90% interval 0.78 to 0.99. Synonymous variants: 72 observed, 73.61 expected, observed/expected ratio (o/e) 0.98, 90% interval 0.81 to 1.19.
Homologues: Orthologues: chimpanzee MRPL22 (99% identical), macaque MRPL22 (96% identical), mouse Mrpl22 (89% identical), rat Mrpl22 (89% identical), dog MRPL22 (89% identical), rabbit MRPL22 (86% identical), guinea pig MRPL22 (83% identical), pig MRPL22 (83% identical), tropical clawed frog mrpl22 (72% identical), zebrafish mrpl22 (67% identical), Drosophila melanogaster mRpL22 (46% identical), Caenorhabditis elegans mrpl-22 (29% identical).
Diseases named in the same sentence as MRPL22 in open-access papers:
MRPL22 is named in the same sentence as 11 diseases in open-access papers, as found by Europe PMC text mining. Sharing a sentence is not in itself a finding about the gene and the disease. The quoted sentences say what the papers report.
B-cell non-Hodgkin lymphoma (1 paper, 2025). The most common type of non-Hodgkin lymphoma. "A LARP1::MRPL22 fusion has been reported to be recurrently expressed in B-cell non-Hodgkin lymphoma; however, its clinical significance remains unclear." (PMID 41373823, 2025).
colorectal cancer (1 paper, 2023). A primary or metastatic malignant neoplasm that affects the colon or rectum. "Furthermore, based on the data from the Protein Atlas, the protein levels of these genes (except MRPL22) are low in colorectal cancer cells." (PMID 37654625, 2023).
endometrial cancer (1 paper, 2025). Primary or metastatic malignant neoplasm involving the endometrium (mucous membrane that lines the endometrial cavity). "Recent studies have also shown that MRPL22 was identified as a shared gene signature for endometrial cancer and polycystic ovary syndrome." (PMID 41334450, 2025).
Hyperglycemia (1 paper, 2025). An increased concentration of glucose in the blood. "The identified signature genes (RPS13, MRPS5, MRPL21, MRPL22, NDUFS3) not only unravel the molecular cascade linking maternal hyperglycemia to fetal vascular dysfunction but also offer tangible targets for diagnostic and therapeutic innovation." (PMID 40727584, 2025).
ischemic stroke (1 paper, 2025). A stroke disorder caused by obstruction of blood flow to the brain, due to thrombotic (local blood clot formation) or embolic (due to a blood clot or other material traveling from another site) event. "Previous studies have shown that MRPL22, as an immune-related gene, participates in the T cell receptor signaling pathway and was identified as a hub gene for the diagnosis of ischemic stroke." (PMID 41334450, 2025).
lung adenocarcinoma (1 paper, 2021). A carcinoma that arises from the lung and is characterized by the presence of malignant glandular epithelial cells. "Upregulation of MRPL22 (HR = 1.5, p = 0.0048), MRPL28 (HR = 1.5, p = 0.0098), MRPL21 (HR = 1.7, p = 0.001), MRPL12 (HR = 1.7, p = 0.00059), MRPS12 (HR = 1.6, p = 0.002), and MRPL17 (HR = 1.5, p = 0.0051) were correlated with poor overall survival in lung adenocarcinoma." (PMID 34925439, 2021). "The Cytoscape with cytoHubba tool kits, GEPIA, and c-BioPortal analysis suggested that upregulated hub genes of MRPL22, MRPL28, MRPL21, MRPL12, MRPS12, and MRPL17 are correlated with poor overall survival and may play a key role by cooperating with ALDOA in lung adenocarcinoma." (PMID 34925439, 2021).
MRPL22 also shares sentences with these, for which no sentence is quoted: asthma (1 paper); cancer (1); hypothyroidism (1); polycystic ovary syndrome (1); Sepsis (1).